COL16A1 (collagen type XVI alpha 1 chain)
Description:
Involved in mediating cell attachment and inducing integrin-mediated cellular reactions, such as cell spreading and alterations in cell morphology.
Synonyms: FP1572; 447AA
Tractability: Antibody: UniProt places it where antibodies can reach, with high confidence; its Gene Ontology location is reachable by antibodies, with high confidence; UniProt predicts a signal peptide or a membrane-spanning region.
Gene: Protein-coding gene on chromosome 1 (31,652,260 to 31,704,319, reverse strand). Ensembl gene ENSG00000084636.
Subcellular location: Secreted, extracellular space, extracellular matrix
Subcellular location (Human Protein Atlas): Golgi apparatus; Cytosol; Predicted to be secreted
Pathways (Reactome):
Extracellular matrix organization: Collagen biosynthesis and modifying enzymes; Collagen chain trimerization; Collagen degradation; Integrin cell surface interactions
Gene Ontology:
Molecular function: extracellular matrix structural constituent conferring tensile strength; integrin binding; protein binding
Biological process: cell adhesion; cell adhesion mediated by integrin; integrin activation; positive regulation of focal adhesion assembly; extracellular matrix organization; female pregnancy; integrin-mediated signaling pathway
Cellular component: extracellular matrix; basement membrane; collagen type XVI trimer; endoplasmic reticulum lumen; extracellular region; microfibril
Genetic constraint (gnomAD): Loss-of-function variants: 179 observed, 255.21 expected, observed/expected ratio (o/e) 0.7, 90% interval 0.62 to 0.79. The upper end of that interval is the gene's LOEUF score, 0.79, which puts it in group 3 of 6, group 1 being the genes least tolerant of losing a copy. Missense variants: 1,874 observed, 2,092.8 expected, observed/expected ratio (o/e) 0.9, 90% interval 0.86 to 0.93. Synonymous variants: 719 observed, 766.95 expected, observed/expected ratio (o/e) 0.94, 90% interval 0.88 to 1.
Homologues: Orthologues: chimpanzee COL16A1 (99% identical), macaque COL16A1 (97% identical), rabbit COL16A1 (91% identical), pig COL16A1 (91% identical), dog COL16A1 (90% identical), rat Col16a1 (88% identical), mouse Col16a1 (88% identical), guinea pig COL16A1 (69% identical). Paralogues in human: COL4A5 (31% identical), COL4A1 (30% identical), COL4A2 (30% identical), COL4A6 (29% identical), COL4A3 (29% identical), COL7A1 (29% identical), COL5A1 (28% identical), COL11A1 (28% identical), COL11A2 (27% identical), COL5A3 (27% identical), COL4A4 (26% identical), COL2A1 (26% identical), and 25 more.
Diseases named in the same sentence as COL16A1 in open-access papers:
COL16A1 is named in the same sentence as 29 diseases in open-access papers, as found by Europe PMC text mining. Sharing a sentence is not in itself a finding about the gene and the disease. The quoted sentences say what the papers report.
Obesity (3 papers, 2015 to 2022). Accumulation of substantial excess body fat. "Consistent with findings from the early-stages of diet-induced obesity studies, our network analysis identified increased expression of common collagen-related ECM transcripts COL1A1, COL3A1, COL16A1, COL4A4, and COL6A3." (PMID 26678390, 2015).
asthma (2 papers, 2020 to 2024). "Basal EpCs were detected to interact with fibroblast COL16A1, a gene which has been implicated in GWAS of CRSwNP and asthma." (PMID 38444858, 2024). "After this study was performed, new GWASs and functional annotation analysis have been published with new interesting asthma loci such as TNF receptor superfamily member 8 (TNFRSF8 ), and Collagen Type XVI Alpha 1 Chain (COL16A1 ), and more studies are to come." (PMID 33133517, 2020).
glioma (2 papers, 2015 to 2021). A benign or malignant brain and spinal cord tumor that arises from glial cells (astrocytes, oligodendrocytes, ependymal cells). "Most notably, compared to the expression of flanking exons in UMSCC-74B cells, CELF1 depletion caused a 5-fold increase in the exclusion of exon 49 in COL16A1 (collagen type XVI), which encodes an extracellular matrix protein involved in oral cancer cell proliferation and glioma cell invasion." (PMID 26498364, 2015).
Hepatic fibrosis (2 papers, 2025). The presence of excessive fibrous connective tissue in the liver. "Classical fibrotic mediators and markers (including Tgfb1, Timp1, and Vcam1), collagen of the ECM (including Col4a1, Col4a2, Col16A1, and Col18a1) and cell surface adhesion and signaling integrin (Itga2, Itga5) were found to be differentially expressed in the enriched hepatic fibrosis pathways." (PMID 39747668, 2025).
ovarian carcinoma (2 papers, 2015 to 2023). A malignant neoplasm originating from the surface ovarian epithelium. "COL16A1 was identified as a risk model in a prognostic model of OC, and its expression was significantly increased in ovarian cancer tissue and predicted poor prognosis." (PMID 36642706, 2023). "From this module, COL16A1, COL3A1, and COL1A2 are likely to be ovarian cancer genes, as they are cancer genes and are enriched with at least one pathway containing ovarian cancer genes." (PMID 25611546, 2015).
astrocytoma (1 paper, 2025). "Among the 19 collagen gene transcripts that were profiled, COL16A1, COL8A1, and COL2A1 exhibited higher levels in the GBM tissue versus the grade III astrocytoma sample." (PMID 41366031, 2025).
endometrial adenocarcinoma (1 paper, 2021). "The results of RT-qPCR detection showed that the expression of miR-543 was upregulated, and the mRNA expression of COL16A1 was decreased in primary endometrial epithelial cells and endometrial adenocarcinoma cells." (PMID 33860034, 2021). "In endometrial epithelial cells and endometrial adenocarcinoma cells, after the overexpression of miR-543, the mRNA expression of vimentin, COL16A1, α-SMA, and Fibronectin decreased, while the mRNA expression of CDH1 increased, while miR-543 inhibitor played the opposite role." (PMID 33860034, 2021).
hepatic (1 paper, 2025). "Differential regulation of the hepatic stellate cell activation and hepatic fibrosis pathways was largely driven by upregulation of 17 collagen isoforms, including COL12A1, COL15A1, COL16A1, and COL1A1." (PMID 40040391, 2025).
ischemic cardiomyopathy (1 paper, 2016). Ischemic cardiomyopathy is a cardiomyopathy in which a weakness in the muscle of the heart due to inadequate oxygen delivery to the myocardium with coronary artery disease being the most common cause. "We carried out RT-qPCR and western blot analyses focusing on COL8A1, related significantly with LV mass index, and on COL16A1, the new collagen related with ventricular dysfunction in ischemic cardiomyopathy (ICM)." (PMID 27936202, 2016).
keloid (1 paper, 2025). An irregularly shaped, elevated mark on the skin caused by deposits of excessive amounts of collagen during wound healing. "The results of the FOXP1-Cut&Tag experiment in keloid fibroblasts revealed that FOXP1 is associated with the SEs of SERPINH1, MMP14, COL5A1, COL16A1, and SPARC, all of which exhibited significant signal enrichment in their SE regions." (PMID 40702440, 2025).
macular edema (1 paper, 2023). "RPCs increased the expression of Col8a1, Col14a1, Col16a1 and Col18a1, among them, Col18a1 has been reported to be associated with macular edema, neovascularization, and retinal detachment in DR26." (PMID 37670124, 2023).
oral squamous cell carcinoma (1 paper, 2022). "As for the transcriptomics level, researchers from Medical University of South Carolina validated that at least in oral squamous cell carcinoma, the alteration of the gene expression of COL16A1 may promote tumor growth via interacting with the RNA-binding protein CELF1." (PMID 35155435, 2022).
osteoarthritis (1 paper, 2022). A noninflammatory degenerative joint disease occurring chiefly in older persons, characterized by degeneration of the articular cartilage, hypertrophy of bone at the margins and changes in the synovial membrane. "COL16A1 was associated to osteoarthritis in humans, while polymorphisms in COL8A gene were associated to the loss of function during embryogenesis leading to congenital vertebral malformations." (PMID 36003650, 2022).
osteosarcoma (1 paper, 2021). A usually aggressive malignant bone-forming mesenchymal neoplasm, predominantly affecting adolescents and young adults. "In the case of module 3 genes associated with osteosarcoma, eight are found in COSMIC (LUM, COL6A3, TNC, CALU, COL16A1, OMD, ITGB5, and DPSYL3), and two (CDH11 and OMD) are oncogenes found in OncoKB." (PMID 34570764, 2021).
renal adenocarcinoma (1 paper, 2020). "Except for COL16A1, which does not have the pathological IHC of renal adenocarcinoma, the other six key gene proteins showed consistent CAFs-containing stromal high expression characteristics in IHC of renal adenocarcinoma." (PMID 33634098, 2020).
serous ovarian cancer (1 paper, 2024). "Regarding the constituents of our 7-gene signature, CACNA1C is overexpressed in high-grade serous ovarian cancer and correlated with prognosis, whereas COL16A1 expression is significantly correlated with progression-free survival in advanced serous ovarian cancer." (PMID 38481252, 2024).
tumor (8 papers, 2017 to 2025). "An additional 4-month exposure to the BRAF inhibitor vemurafenib resulted in a highly drug resistant tumor that showed 3 additional new DNA mutations in the genes BUB1B, PINK1, and COL16A1." (PMID 28173755, 2017). "Of the 78 available sequenced tumor samples, we found increases in the mutation frequency of all 3 of these genes: BUB1B increased from 2 to 7% of patients, PINK1 from 1 to 7% of patients, and COL16A1 from 4 to 11% of patients." (PMID 28173755, 2017). "Similarly, two differentially expressed collagen genes (COL9A2 and COL16A1) exhibited negative fold-changes in transcript counts for the grade 3 tumor sample." (PMID 41366031, 2025). "Conversely, 26 genes, including mediators of epithelial–mesenchymal transition (i.e., COL6A1/A2, COL16A1, MFAP5, MMP11), were co-expressed in tumor tissue but not in NAU." (PMID 35626146, 2022). "On the other hand, Col4a1, Col4a3, Col4a5, Col5a3, Col11a2, Col14a1, Col15a1, Col16a1, and Col22a1 were found in normal ECM but not in tumor ECM; Col25a1 was found only in tumor ECM but not in normal ECM." (PMID 36547361, 2022).
cancer (6 papers, 2015 to 2024). A tumor composed of atypical neoplastic, often pleomorphic cells that invade other tissues. "COL16A1 was found to be one of eight genes in a signature that predicts survival in OC and was validated to be highly expressed in cancer tissues compared with normal tissues." (PMID 33193589, 2020). "The highest expression of genes encoding Col1a1-2, Col3a1, Col4a1, Col4a2, Col5a1, Col5a2, Col6a1, Col8a1, Col9a3, Col10a1, Col12a1, Col14a1, Col15a1, Col16a1, Col18a1, and Col28a1 were detected in untreated tumors, whose landscapes were dominated by Krt8+ cancer cells." (PMID 39372930, 2024). "Immunohistochemistry results indicated significantly elevated GALP, CACNA1C, COL16A1, PENK, C4BPA, PSMA2, and CXCL9 expression in cancer tissues." (PMID 38481252, 2024). "Immunohistochemistry results indicated significant upregulation of GALP, CACNA1C, COL16A1, PENK, C4BPA, PSMA2, and CXCL9 in cancer tissues." (PMID 38481252, 2024).
infection (2 papers, 2025). The state of being infected such as from the introduction of a foreign agent such as serum, vaccine, antigenic substance or organism. "Genes involved in cell adhesion and structural components, including laminins (LAMA2), elastin (ELN), and collagens (COL16A1, COL13A1, COL8A1) were significantly downregulated at 24 hours post-infection (hpi) in both variants." (PMID 41200555, 2025).
COL16A1 also shares sentences with these, for which no sentence is quoted: connective tissue disorder (2 papers); pulmonary fibrosis (2); Alzheimer disease (1); chronic obstructive pulmonary disease (1); COVID-19 (1); Hypoglycemia (1); lung carcinoma (1); lymph node metastasis (1); oral cancer (1); retinal detachment (1).